TTC38 (tetratricopeptide repeat domain 38)
Synonyms: FLJ20699; LL22NC03-5H6.5
Tractability: PROTAC: ubiquitination databases record sites on it; its protein half-life has been measured.
Gene: Protein-coding gene on chromosome 22 (46,267,961 to 46,295,097, forward strand). Ensembl gene ENSG00000075234.
Subcellular location (Human Protein Atlas): Cytosol
Gene Ontology:
Molecular function: protein binding
Cellular component: extracellular exosome
Genetic constraint (gnomAD): Loss-of-function variants: 62 observed, 61.83 expected, observed/expected ratio (o/e) 1, 90% interval 0.82 to 1.24. The upper end of that interval is the gene's LOEUF score, 1.24, which puts it in group 5 of 6, group 1 being the genes least tolerant of losing a copy. Missense variants: 573 observed, 619.01 expected, observed/expected ratio (o/e) 0.93, 90% interval 0.86 to 0.99. Synonymous variants: 254 observed, 247.98 expected, observed/expected ratio (o/e) 1.02, 90% interval 0.92 to 1.14.
Homologues: Orthologues: chimpanzee TTC38 (98% identical), macaque TTC38 (95% identical), pig TTC38 (89% identical), rat Ttc38 (88% identical), dog TTC38 (88% identical), mouse Ttc38 (87% identical), guinea pig TTC38 (85% identical), rabbit TTC38 (80% identical), tropical clawed frog ttc38 (63% identical), zebrafish ttc38 (59% identical), Caenorhabditis elegans Y54G11A.7 (37% identical), Caenorhabditis elegans Y54G11A.4 (35% identical).
Diseases named in the same sentence as TTC38 in open-access papers:
TTC38 is named in the same sentence as 2 diseases in open-access papers, as found by Europe PMC text mining. Sharing a sentence is not in itself a finding about the gene and the disease. The quoted sentences say what the papers report.
experimental autoimmune encephalomyelitis (1 paper, 2020). An autoimmune demyelinating disease of the central nervous system that is produced experimentally in animals by the injection of homogenized brain or spinal cord in Freund's adjuvant. "A recent proteome of mouse with experimental autoimmune encephalomyelitis (EAE) identified the downregulation of Ttc38 in the brain." (PMID 32915913, 2020).
cancer (2 papers, 2010 to 2024). A tumor composed of atypical neoplastic, often pleomorphic cells that invade other tissues. "Unfortunately, no reports on the function of the Ring Finger Protein, Transmembrane 1 (RNFT1), and Tetratricopeptide Repeat Domain 38 (TTC38) or their role in cancer have been found so far." (PMID 38163849, 2024).